VCAN (versican)
Diseases named in the same sentence as VCAN in open-access papers (continued):
Sharing a sentence is not in itself a finding about the gene and the disease.
non-small cell lung carcinoma (8 papers, 2012 to 2025). A group of at least three distinct histological types of lung cancer, including non-small cell squamous cell carcinoma, adenocarcinoma, and large cell carcinoma. "A recent study has identified plasma exosomal versican as a potential diagnostic marker for non-small cell lung cancer." (PMID 40612948, 2025). "In non-small cell lung cancer, versican has been shown to be associated with an unfavourable prognosis but is not considered to be an independent indicator of patient survival." (PMID 23082892, 2012).
thoracic aortic aneurysm (8 papers, 2019 to 2025). An aneurysm formed in the wall of the proximal portion of the descending aorta proceeding from the arch of the aorta. "Consistent with the results of our study, previous reports showed the degradation of versican in aortic tissues from patients with thoracic aortic aneurysms and dissections." (PMID 36144730, 2022). "For the case of thoracic aortic aneurysms and dissections (TAADs), Cikach et al6used ribonucleic acid in situ hybridization studies to demonstrate a rise in gene expression of aggrecan and versican in humans and in mouse models." (PMID 35933987, 2022). "The proteolysis of versican by ADAMTS4 also contributes to fetal membrane rupture at parturition, as well as the development of thoracic aortic aneurysms and dissections." (PMID 40002887, 2025). "ADAMTS4 protein and mRNA are expressed at higher levels in thoracic aortic aneurysm and dissection tissues than in control aortic tissues, and increased ADAMTS4 levels can degrade versican and facilitate macrophage invasion." (PMID 32095376, 2020).
glioblastoma (7 papers, 2017 to 2026). The most malignant astrocytic tumor (WHO grade IV). "Previous research reports have indicated that VCAN promotes the generation of new blood vessels in glioblastoma." (PMID 37108649, 2023). "The expression levels of circ_COL1A2, circ_PTN, circ_VCAN, circ_PLOD2, circ_SMO, circ_CLIP2, circ_GLIS3, and circ_EPHB4 in glioblastoma (GBM) are significantly higher than those in normal tissues." (PMID 30064463, 2018). "Eight circRNAs, including circ_COL1A2, circ_PTN, circ_VCAN, circ_SMO, circ_PLOD2, circ_GLIS3, circ_EPHB4, and circ_CLIP2 showed significantly higher expression in glioblastoma (GBM) than in normal tissues." (PMID 28969099, 2017).
Lewis lung carcinoma (7 papers, 2010 to 2020). "In Lewis lung carcinoma, stromal cell-derived versican and its fragment, versikine are associated with increased angiogenesis as part of the inflammatory response contributing to this tumor." (PMID 32265939, 2020). "Extracellular matrix protein versican derived from Lewis lung carcinoma was found to activate bone marrow-derived macrophages by binding to TLR2, leading to secretion of inflammatory cytokines such as TNF-α to promote metastasis." (PMID 32382015, 2020). "Recently, the importance of stromal HA-binding proteins was demonstrated for the proteoglycan versican, which triggers the invasion and retention of inflammatory cells in Lewis lung carcinoma and supports metastasis." (PMID 21429221, 2011). "By activating TLR2:TLR6 complexes and inducing TNF-α secretion in myeloid cells, versican strongly enhances Lewis lung carcinoma metastatic growth." (PMID 20145615, 2010).
myeloma (7 papers, 2019 to 2025). "Dhakal and collaborators evaluated VCAN proteolysis in the post-transplant survival of patients with myeloma and showed that the group with low VKINE expression had better overall survival and response rates." (PMID 39682243, 2024). "On the other hand, in myelomas, versican is proteolyticaly processed to the DAMP versikine, which induces the secretion of IL-1β and IL-6 by human myeloma marrow-derived macrophages (MAMs)." (PMID 31068944, 2019).
osteosarcoma (7 papers, 2014 to 2024). A usually aggressive malignant bone-forming mesenchymal neoplasm, predominantly affecting adolescents and young adults. "Consistent with our analyses of osteosarcoma patient data, prior studies have shown that elevated levels of versican are associated with poor prognosis for patients with a wide range of malignant tumors." (PMID 34631514, 2021). "The HA-binding PG, versican, is likewise overexpressed in osteosarcoma tissues relative to healthy bone tissue and facilitates osteosarcoma cell migration." (PMID 34069554, 2021). "Using this system, we identify the versican/ECM network dysregulation as a potential contributor to osteosarcoma circulating tumor cell metastasis." (PMID 34631514, 2021). "Versican expression is prognostic for a poorer metastasis-free and overall survival in patients with osteosarcoma." (PMID 34631514, 2021). "TGF-β2 enhances versican expression in fibrosarcoma and osteosarcoma cells and IL-1β increases versican levels in lung fibroblasts." (PMID 28035060, 2017). "Also consistent with a role in extravasation and metastasis, an elevated versican expression is prognostic for a poorer metastasis-free survival and overall survival in osteosarcomas." (PMID 34631514, 2021). "VCAN was also previously shown to suppress tumor cell growth in mesothelioma, osteosarcoma, prostate, and other tumor cell lineages suggesting it may be a promising therapeutic target for preclinical development." (PMID 25587024, 2014). "Furthermore, scRNA-seq analysis of six treatment-naïve osteosarcoma tumors, combined with a dataset of 22,035 cells from six osteosarcoma tumors, demonstrated that MDSCs were among the most abundant in the immunosuppressive milieu, as evidenced by MDSC hallmark genes (VCAN, CLEC4E, and CSF3R)." (PMID 39359731, 2024). "In primary osteosarcoma tissues, classical (CD14+D16-) monocytes with an overexpression of VCAN and S100A8/9/12 exhibit pro-inflammatory functions, whereas the non-classical (CD14-D16+) monocytes with high levels of CDKN1C, LILRB2, TGAL, and CX3CR1 expression exhibit the anti-inflammatory effects." (PMID 39359731, 2024).
COVID-19 (6 papers, 2021 to 2024). A disease caused by infection with severe acute respiratory syndrome coronavirus 2. "cMono expressing VCAN, which is implicated in cytokine release, were specifically increased in COVID-19 and reduced in influenza, while complement component C1Q-expressing ncMono were increased in influenza and sepsis, but not in COVID-19." (PMID 35216673, 2022). "We found specific differences for other populations, for example increased complement expressing (C1Q) ncMono in sepsis and extracellular matrix protein versican expressing cMono (mitohiVCANhi) in COVID-19." (PMID 35216673, 2022). "A single cell study showed increased SIGLEC1 and VCAN in CD14+ monocytes from COVID-19 donors compared to healthy controls." (PMID 34108966, 2021). "In the context of COVID-19, using our method, we were able to identify VCAN and TLR2 as potential targets for immunomodulatory attempts, which was further confirmed by analyzing two independent patients with severe symptomatology." (PMID 33536217, 2021). "Thus, VCAN constitutes a plausible, novel target gene for modulating the hyperinflammatory response in patients with COVID-19 with severe symptomatology." (PMID 33536217, 2021). "Last, computational perturbation of genes involved in causal feedback loops identified versican (VCAN), an extracellular matrix glycoprotein, and Toll-like receptor 2 (TLR2) as novel target proteins for alleviating the hyperinflammatory response in patients with COVID-19 with severe symptomatology." (PMID 33536217, 2021). "We observed that COVID-19 cases presented significant increased deposition of collagen, fibronectin, versican, and TGF-β, and decreased decorin density when compared to non-COVID-19 cases of similar MV duration." (PMID 37964271, 2023). "All assessed ECM components, collagen (p < 0.0001; η2 = 0.38), fibronectin (p < 0.0001; η2 = 0.34), versican (p = 0.013; η2 = 0.15), decorin (p = 0.028; η2 = 0.12), and TGF-β (p = 0.018; η2 = 0.14), had their expression influenced by COVID-19, except the elastic fibres (p = 0.271; η2 = 0.03)." (PMID 37964271, 2023). "The fibronectin (p < 0.0001) and the versican (p = 0.044) densities were increased in the COVID-19 cases compared to the non-COVID-19, whereas the decorin density was decreased in the COVID-19 cases compared to the non-COVID-19 (p = 0.033)." (PMID 37964271, 2023). "In this study, we have shown that COVID-19 cases present increased deposition of collagen, fibronectin, versican, and TGF-β in the lungs when compared to non-COVID-19 ARDS cases of similar ventilation duration." (PMID 37964271, 2023).
diabetic kidney disease (6 papers, 2012 to 2025). Progressive kidney disorder caused by vascular damage to the glomerular capillaries, in patients with diabetes mellitus. "In kidney biopsies from patients with diabetic nephropathy (DN) versican expression was increased 1.4 fold as compared to patients with minimal change disease (MCD) (p<0.05)." (PMID 23024773, 2012). "In transcriptomics profiles of renal tissue versican was positively correlated with (i) histological parameters in kidney biopsies, (ii) progressive decline of renal function in proteinuric kidney diseases, and (iii) impaired renal function and histology scores in diabetic nephropathy." (PMID 23024773, 2012). "Nephroseq v5 webserver predicted the over expression of FN1, SPARC, LUM, VCAN, and POSTN with fold change of 2.808, 1.655, 6.25, 1.77, and 3.324 in diabetic nephropathy respectively." (PMID 34557161, 2021).
heart failure (6 papers, 2014 to 2024). Inability of the heart to pump blood at an adequate rate to meet tissue metabolic requirements. "Previous studies by our group have reported elevated levels of versican in pressure overload, and by others in heart failure, which are disease conditions associated with cardiac fibrosis." (PMID 38076279, 2023). "Versican expression and cleavage was also increased following stimulation of cardiac cells with cytokines associated with heart failure, indicating inflammation as one of the regulators for versican homeostasis." (PMID 31547598, 2019). "The p150 versican fragment is associated with myocardial edema, a feature of heart failure." (PMID 31547598, 2019). "This plays a role in heart failure as the CD44 pathway plays a role in heart failure and it has been found that versican accumulates in patients with ischemic heart failure." (PMID 39194478, 2024). "The extracellular matrix proteoglycan versican is elevated in heart failure and suggested to be a target for treatment." (PMID 38076279, 2023). "Synthesis of ADAMTS4 and versican in cardiac cells was induced in vitro by TNF-α and IL-1β, cytokines found in enhanced levels in the failing myocardium, suggesting inflammation as a trigger for ADAMTS-mediated versican fragmentation in heart failure." (PMID 24595230, 2014). "Moreover, targeting versican through chondroitin sulfate chains or its cleavage has improved cardiac function in a heart failure model." (PMID 38076279, 2023). "Our study showing the dynamic profile of versican and DPEAAE in cardiac fibrosis development may contribute to further development of heart failure therapies." (PMID 38076279, 2023). "Although it has been shown that the large hydrophilic proteoglycans versican and aggrecan reside in the embryonic cardiac ECM, and that versican is expressed in cardiomyocytes and the adult heart, their role in heart failure development is unknown." (PMID 24595230, 2014). "Moreover, the versican cleavage product (DPEAAE fragment) generated by ADAMTS (a disintegrin and metalloproteinase with thrombospondin motifs) enzymes may also be involved in development of cardiac fibrosis and heart failure." (PMID 38076279, 2023).
idiopathic pulmonary fibrosis (6 papers, 2011 to 2024). Idiopathic pulmonary fibrosis (IPF) is a nonneoplastic pulmonary disease that is characterized by the formation of scar tissue within the lungs in the absence of any known cause. "Previous studies have reported that versican precedes collagen expression in pulmonary fibrosis, and that it modulates collagen fibrillogenesis by direct binding." (PMID 38076279, 2023). "Increased accumulation of versican and decorin has been also reported in patients with pulmonary fibrosis." (PMID 26751072, 2016). "Another report has shown, in a rat model of a bleomycin-induced pulmonary fibrosis, that levels of versican, heparin sulfate, and fibromodulin are increased in fibrotic lungs." (PMID 26583132, 2015). "Previous studies evaluating ECM changes in ARDS have shown altered alveolar septa with lung fibrosis and increased alveolar content of collagen and elastic fibers, fibronectin and versican in exudative and/or proliferative phases of lung injury." (PMID 21211006, 2011). "We identified one transcript, killer cell lectin like receptor 1 (KLRF1), as differentially expressed between idiopathic pulmonary fibrosis (IPF) and systemic sclerosis-associated ILD (SSc-ILD), and identified two transcripts (VCAN, LTK) associated with IPF expression against other ILD subtypes." (PMID 39625896, 2024). "Evidence shows that the deposition of versican, a chondroitin sulfate-containing proteoglycan, is significantly increased in the ECM of lung lesions from patients with idiopathic pulmonary fibrosis." (PMID 26583132, 2015).
keloid (6 papers, 2007 to 2026). An irregularly shaped, elevated mark on the skin caused by deposits of excessive amounts of collagen during wound healing. "Subsequent network topology analysis through CytoHubba identified six hub genes (IL6, POSTN, VCAN, COL11A1, HAPLN1, TNC) via three methods of calculation respectively (Closeness, Degree and EPC), representing key regulatory nodes in the keloid." (PMID 41544047, 2026). "The fact that some proteoglycans related to skin mechanical forces (e.g., ASPN, VCAN, and OMD) were also overexpressed in keloids proved the interaction between skin mechanical disorder and keloid formation again." (PMID 35435317, 2022).
lung adenocarcinoma (6 papers, 2021 to 2025). A carcinoma that arises from the lung and is characterized by the presence of malignant glandular epithelial cells. "It was observed that the high expression of Versican was associated with an overall poor prognosis in Lung adenocarcinoma in comparison to Lung squamous cell carcinoma and various other solid tumors viz." (PMID 37784035, 2023). "A previous study showed that VCAN combined with miRNA-30a-5p could arrest tumor metastasis via cell adhesion in lung adenocarcinoma." (PMID 41415585, 2025). "As the increased levels of THSB2, VCAN, and TNC on sEVs were found to indicate lung adenocarcinoma patients, we combined these biomarkers and explored their usage as a signature in identifying malignant and benign lung lesions." (PMID 36394090, 2022).
metastatic tumors (6 papers, 2007 to 2025). "In a previous study, the density of VCAN expression was stronger in metastatic tumors compared to the primary tumor." (PMID 34356118, 2021). "We found a marked production of CCL2 and CXCL1 in the lung, in parallel with macrophage influx, increased metastatic disease and high versican expression in the lung tissue." (PMID 31334111, 2019). "The results of the present study indicate that the G3 domain of versican influences breast cancer tumor cell adhesion, migration, proliferation and metastatic tumor burden." (PMID 17662123, 2007). "COL3A1, COL5A2, VCAN, CCND2, JAG2, and VTN showed consistent positive correlations with all three scores in both primary and metastatic tumors, suggesting their involvement in enhancing stromal support and recruiting immune cells." (PMID 40943183, 2025). "We looked at the TGFβ-1, CXCR4, BMP1, VCAN, and WNT2 expression profiles in a few BC datasets related to primary and metastatic tumors." (PMID 41348904, 2025). "TGFβ-1, CXCR4, BMP1, VCAN, and WNT2 are more expressed in original tumors compared to metastatic tumors, according to the data." (PMID 41348904, 2025).
myocardial infarction (6 papers, 2012 to 2026). Gross necrosis of the myocardium, as a result of interruption of the blood supply to the area, as in coronary thrombosis. "Versican was reported to promote cell proliferation and myocardial regeneration in a murine myocardial infarction model." (PMID 40459298, 2026). "This suggests active versican degradation (versicanolysis) mediated by ADAMTS1 during cardiac remodeling following myocardial infarction, further confirming ADAMTS1′s involvement in the pathological process of human myocardial infarction." (PMID 41440846, 2025). "Versican has consistently been shown to be expressed in injured and healing tissues, including after skin injury by incision or burn, following myocardial infarction, in stented arteries and in cancers, among others." (PMID 26176948, 2015). "Interestingly, levels of VCANM were not exclusively associated to cardiovascular mortality, despite the previous findings that versican fragmentation was increased in cardiovascular diseases such as acute myocardial infarction and coronary calcification." (PMID 25354390, 2014).
Marfan syndrome (5 papers, 2020 to 2025). A disorder of the connective tissue. "A recent study demonstrated that VCAN contributes to aortic disease in Marfan syndrome (MFS) by triggering Nos2 through Akt activation in vivo." (PMID 40227858, 2025). "Marfan Syndrome-associated MVP is accompanied by myxomatous changes in the ECM as indicated by an abnormal accumulation of proteoglycans, largely decorin, versican and lumican and changes in collagen fibers including increased expression." (PMID 32824919, 2020). "Versican and hyaluronan expression are induced by TGF-β, with increased hyaluronan found in Marfan syndrome patients." (PMID 36012466, 2022).
multiple sclerosis (5 papers, 2020 to 2024). A progressive autoimmune disorder affecting the central nervous system resulting in demyelination. "Alleles associated with lower NDI were associated with larger WMH volume at chr5q14.3 (VCAN) and with higher pulse pressure and lower risk of multiple sclerosis (MS) at chr17q21.2 (STAT3), all at genome-wide significance." (PMID 38811690, 2024). "In multiple sclerosis, lecticans, (namely aggrecan, versican and neurocan) and dermatan sulfate-proteoglycans (DSPGs) are upregulated around the edges of acute lesions alongside astrogliosis." (PMID 36232390, 2022). "Both tenascins interact with various chondroitin sulfate proteoglycans (CSPGs) of the lectican family such as versican and brevican and thus partake in the inhibitory environment that restricts regeneration of myelin, in particular in multiple sclerosis lesions." (PMID 35681468, 2022). "In particular, people with multiple sclerosis on natalizumab had lower CD6, CDCP1, CXCL13, CXCL9, NfL, TNFRSF10a, TNFSF13B and VCAN (P < 0.036)." (PMID 37361716, 2023).
myopia (5 papers, 2024 to 2025). "The most common pathogenic genes responsible for high myopia with RRD were COL2A1 (10.0%, 4/40) and COL11A1 (5.0%, 2/40) and VCAN (5.0%, 2/40)." (PMID 40270540, 2025). "Versican is also involved in ECM synthesis in scleral fibroblasts and is associated with myopia." (PMID 39160465, 2024). "According to the PPI network analysis and protein docking model, the protein of versican interacts with fibrillin‐1, which is the component of ECM; the versican and fibrillin‐1 complex links extracellular microfibrils to other connective tissue networks and may be responsible for high myopia." (PMID 41477247, 2025). "According to our research, patients with pathologic myopia had downregulated expression of XYLT1, VCAN, and SPOCK2 and upregulated expression of TUBA1A and EEF1A1." (PMID 39160465, 2024).
renal cell carcinoma (5 papers, 2017 to 2024). "The growth of renal cell cancer cells can be inhibited by the activation of TNF signaling pathway through the silencing gene VCAN." (PMID 33015179, 2020). "Similarly the proteoglycan versican, coded by the gene VCN seems to be involved in tumor progression and metastasis, as has been shown for renal cell carcinoma." (PMID 29202741, 2017).